MTOR (mechanistic target of rapamycin kinase)
Diseases named in the same sentence as MTOR in open-access papers (continued):
Sharing a sentence is not in itself a finding about the gene and the disease.
glioblastoma (continued). "Consequently, downregulation of the PI3K-Akt/NF-κB/mTOR, STAT3, and CDK6 signaling pathways was reportedly used to abrogate GBM oncogenic properties and re-sensitized aggressive glioblastomas to chemotherapy." (PMID 34572040, 2021). "Specifically, ABA-induced autophagy in glioblastoma cells was mediated by the MAPK/JNK signalling pathway rather than the PI3K/AKT/mTOR axis." (PMID 32577848, 2021). "In line with our findings, previous studies have reported that inhibitors of CDK6 mediated mTOR activation while combined therapy of an mTOR inhibitor and a CDK6 inhibitor synergized to achieve enhanced inhibition of tumor growth in glioblastoma, head and neck and pancreatic cancers." (PMID 34572040, 2021). "However, SB747651A ́s multi-targeting of glioblastoma metabolism, mediated by GSK3 and GYS1, combined with mTOR and CREB inhibition, and a decrease of SOX2 expression, has not previously been described." (PMID 33727611, 2021). "In addition, we explored the mechanistic role of E2F7−EZH2 axis in AKT/mTOR activation, and the results suggested that E2F7 promoted glioblastoma progression via EZH2-mediated PTEN/AKT pathway." (PMID 32814835, 2020). "Next, we asked how mTOR deregulation occurred in TAM‐MG and whether glioblastoma initiating cells (GIC) could play a role, considering that they secrete growth and inflammatory factors that could potentially stimulate mTOR signalling in microglia." (PMID 32567735, 2020). "The prognosis of glioblastoma patients with activated PI3K/AKT/mTOR pathway is poor than patients without oncogenic activation of this pathway." (PMID 32814835, 2020). "The activation of a mitogenic pathway involving a feedback mechanism between mTOR and PI3K/ERK1/2 is important for the tumorigenesis of glioblastoma multiforme and may be involved in 3D spheroid formation in s-μg." (PMID 32070055, 2020). "Glioblastoma (GB) is the most malignant and aggressive form of brain tumor, characterized by frequent hyperactivation of the phosphoinositide 3-kinase (PI3K)/protein kinase B (AKT)/mammalian target of rapamycin (mTOR) signaling pathway." (PMID 33123479, 2020). "Treatment with mTOR(C1) inhibitors such as rapamycin or the dual-kinase inhibitor OSI027 reveal similar findings when comparing the effects in glioblastoma and visceral tumors with higher dosing needed for non-CNS tumors." (PMID 33375117, 2020). "The analysis of the three SEGA-like glioblastomas revealed for cases #2 and #3 a similar pattern of phospho-4E-BP1 and 4E-BP1 expression as in SEGAs, indicating diffuse strong activation of mTOR in these tumors." (PMID 31258848, 2019). "Experimental examination with commercially available inhibitors of the LAL or mTOR pathway has currently not been studied for inhibiting growth and immunosuppressive functions of MDSCs in glioblastoma." (PMID 31225500, 2019). "The antibodies used were first tested in WB on five adult glioblastomas without alterations of the MAPK/TSC/mTOR pathway by NGS, and were confirmed to recognize a specific band at the expected size for both phosphorylated and total 4E-BP1." (PMID 31258848, 2019). "mTOR inhibitors such as rapamycin and its analogs (everolimus (RAD001), deforolimus (AP23573), and temsirolimus (CCI-779)) suppress cellular growth and proliferation and are considered to be effective for glioblastoma treatment." (PMID 31013819, 2019). "Therefore, we compared the effect of carnosine on glioblastoma cell viability, PDK4 expression and signaling molecule phosphorylation with the PI3K inhibitor Ly294,002 and the mTOR inhibitor rapamycin in two cell lines derived from glioblastoma." (PMID 31247000, 2019). "With respect to the signaling pathways involved in the melatonin- and agomelatine-induced autophagy, we found that these effects were independent of the PI3K/AKT/mTOR/p70S6K signaling pathway in glioblastoma cells." (PMID 31870319, 2019).
glioblastoma (continued). "In an attempt to improve efficacy, When replacing rapamycin, an mTOR inhibitor, with GDC-0941, which blocks PI3K, i.e. acts more upstream in a glioblastoma cell culture system, this alternative RIST approach showed higher potency, but upon transferring it to a murine system all potency was lost." (PMID 29371599, 2018). "In glioblastoma, HIF-1α expression is mediated by mammalian target of rapamycin (mTOR)." (PMID 28320399, 2017). "It should be mentioned that mTOR inhibitors have not demonstrated therapeutic potential in clinical trials against glioblastoma so far." (PMID 29259984, 2017). "Using two genetically distinct paediatric glioblastoma cell lines, SF188 and KNS42, in vitro1H-NMR analysis following treatment with the dual pan-Class I PI3K/mTOR inhibitor PI-103 resulted in a decrease in lactate and phosphocholine (PC) levels (P<0.02) relative to control." (PMID 28704425, 2017). "PI3K or PI3K/mechanistic target of rapamycin (mTOR) dual inhibitors (e.g., XL765, wortmannin, PI-103, PX-866, and LY294002) alone or in combination with radiotherapy or chemotherapy substantially inhibited glioblastoma cell growth in preclinical studies." (PMID 29326882, 2017). "In conclusion, we have shown that the in vitro combination of PI3K/mTOR inhibition and TMZ in paediatric glioblastoma cells, independent of molecular characteristics, caused alteration in lactate and choline metabolite levels detected by NMR." (PMID 28704425, 2017). "Taken together, CH12 was combined with rapamycin, leading to a synergistic tumor-suppression effect on EGFRvIII+PTEN− glioblastoma in vivo via attenuating EGFR and the PI3K/AKT/mTOR pathway more effectively and reversing STAT5 activation caused by rapamycin treatment." (PMID 27029073, 2016). "As combined inhibition of Akt and mTOR by perfosine and temsirolimus inhibited murine glioblastoma growth no matter PTEN status, a phase I/II trial in recurrent high-grade gliomais ongoing (NCT01051557)." (PMID 26967052, 2016). "PTEN status affected anti-c-MET therapies to glioblastomas in which PTEN protein expression was frequently low or absent, and combining anti-HGF/c-MET therapies with mTOR inhibitors additively inhibited growth of glioblastoma xenografts." (PMID 25098767, 2014). "Both pediatric glioblastoma cell lines were treated with the selective pan-Class I PI3K inhibitor GDC-0941 which does not significantly inhibit mTOR and is entering Phase II clinical trials." (PMID 25084455, 2014). "There is mounting evidence that the PI3K/AKT/mTOR signaling pathway is activated in pediatric glioblastoma and contributes to resistance to TMZ, thus providing key targets for the treatment of pediatric glioblastoma." (PMID 25084455, 2014). "Blocking both mTOR and PI3K promotes the differentiation of glioblastoma stem-like cells." (PMID 24231729, 2013). "In glioblastoma (GBM) models, studies have shown that the overexpression of miR-4524b-5p downregulates the PI3K/AKT/mTOR signaling pathway, inhibiting the expression of the proliferation-related factor Ki-67." (PMID 40725100, 2025). "BBR-mediated apoptosis blocks the AMPK/mTOR/ULK1 pathway and reduces tumor growth in glioblastoma multiforme (GBM) cells in vivo." (PMID 39309003, 2024).
glioblastoma (continued). "In glioblastoma (GBM), the progression may be associated with alterations in the Wnt, transforming growth factor beta (TGF-β), VEGF, EGFR, cyclin-dependent kinase 2A (CDKN2A), nuclear factor-κB (NF-κB), and phosphatidylinositol-3-kinase (PI3K)/AKT/mammalian target of rapamycin (mTOR) pathways." (PMID 39682237, 2024). "We asked whether our combination regimen, lacking the ability to inhibit mTOR activity in peripheral tissues, could retain the efficacy of RapaLink-1 in treating glioblastoma." (PMID 36104566, 2022). "Understanding the regulation of mTOR signaling in glioblastoma may promote the development of novel strategies for targeting the mTOR pathway." (PMID 35239512, 2022). "However, it is unclear whether LSD1 can regulate the AKT/mTOR and mitogen-activated protein kinase (MAPK) signaling pathways to affect the proliferation of glioblastoma cells." (PMID 35042538, 2022). "Therefore, in the present study, we questioned whether cells from glioblastoma multiforme (GBM), a lethal brain neoplasm, wherein mTOR is upregulated and autophagy is suppressed, may overexpress α-syn." (PMID 35326535, 2022). "LINC00470 plays an oncogenic role in glioblastoma multiforme (GBM)-derived exosome by binding to miR-580-3p, regulating the levels of WEE1 and activating the PI3K/AKT/mTOR pathway." (PMID 36338993, 2022). "Indeed, we observed upregulation of PI3K-Akt signaling pathway molecules, including phosphorylated PI3K, Akt, and mTOR, post glioblastoma-derived EV treatment in an approximately time-dependent manner, indicating the induction of PI3K-Akt-mTOR signaling in mNPCs by U87-EVs." (PMID 35022057, 2022). "We here examine two GBM cell lines MO59K and MO59J derived from the same glioblastoma biopsy specimen regarding their response to irradiation and simultaneous DNA-PK/PI3K/mTOR inhibition by PI-103." (PMID 34763650, 2021). "Moreover, the EGFR downstream pathways phosphatidylinositol-4,5-bisphosphate 3-kinase (PI3K)-AKT-mechanistic target of rapamycin kinase (mTOR) signaling and mitogen-activated protein kinase (MAPK) signaling are prominently deregulated and favor therapy resistance in glioblastoma." (PMID 34771501, 2021). "Therefore, it could be speculated that the HSVtk/GCV system promotes neural differentiation of glioblastoma, and this is mediated by the PI3K/AKT/mTOR-related pathway." (PMID 34370752, 2021). "We also mined the clinical data of glioblastoma cohorts in TCGA, PanCancer Atlas and found that alterations in mTOR, STAT3, and CDK6 constituted 5% of the genetic alteration occurring in GBM patients." (PMID 34572040, 2021). "Our bioinformatics studies by Targetscan 7.1 and miRwalk 2.0 site have predicted that miR-548x and miR-4698 could simultaneously target 3ʹUTR of PI3KCB, PI3KCA, PDK1, AKT1, mTOR, MDM2, Rheb, and CREB1 genes that some of them were upregulated in glioblastoma sample according TCGA deta." (PMID 32005873, 2020). "According to our bioinformatics studies in the TargetScan 7.1 and miRwalk 2.0 database, we predicted that some miRNAs, as well as miR-548x and miR-4698 could target some genes that are overactive in the PI3K/AKT pathway (PI3KCB, PI3KCA, PDK1, AKT1, Rheb, MDM2, mTOR, and CREB1) in glioblastoma." (PMID 32005873, 2020). "Targeting the PI3K-AKT-mTOR pathway which is universally altered in glioblastoma has also been unsuccessful and showed no improved outcomes in both newly diagnosed and recurrent glioblastoma using PI3K inhibitors and mTOR inhibitors." (PMID 33202642, 2020). "Likewise, the results of clinical trials exploring EGFR and mTOR inhibition in unselected glioblastoma patients with a one-size-fits-all approach were negative." (PMID 32756332, 2020). "We aimed to elucidate new role of mTOR in EGFR-mutant (EGFR-mut) non-small cell lung cancer (NSCLC) and glioblastoma (GBM) with a focus on tumor microenvironments." (PMID 32923403, 2020).
glioblastoma (continued). "However, efforts on metabolic reprogramming to target mTOR or PPARγ by MDSCs are currently not done in glioblastoma models." (PMID 31225500, 2019). "As carnosine did not increase the expression of the reporter gene, this observation supports the assumption resulting from the viability assays, that carnosine must mediate its physiological effects without influencing PI3K/Akt/mTOR in the glioblastoma cells used." (PMID 31247000, 2019). "In contrast to the results of the current study, previous studies showed that NF-κB could negatively regulate mTOR at the transcriptional level through receptor interacting protein 1 (RIP1), which played a key role in NF-κB activation in a glioblastoma cell line." (PMID 26771918, 2016). "While treatment of glioblastoma includes radiotherapy and chemotherapy, generally, glioblastomas (GBMs) are resistant to the current therapeutics due to the hyperactivation of the PI3K-Akt-mTOR survival pathway by excessive stimulation via growth factor receptors and Ras." (PMID 24905404, 2014). "In a phase I trial, the safety and tolerability of therapy with the mTOR inhibitor everolimus in combination with radiation and temozolomide (TMZ) was evaluated in patients with newly diagnosed glioblastoma multiforme (GBM)." (PMID 24717239, 2014). "Furthermore, frequently the promising in vitro data regarding mTOR inhibition in Glioblastoma cells does not translate well into an in vivo setting (for example)." (PMID 26056598, 2014). "We show that coibamide A induces autophagosome accumulation in human glioblastoma cell types and MEFs via an mTOR-independent mechanism; no change was observed in the phosphorylation state of ULK1 (Ser-757), p70 S6K1 (Thr-389), S6 ribosomal protein (Ser-235/236) and 4EBP-1 (Thr-37/46)." (PMID 23762328, 2013). "Interestingly, in multidimensional analysis in glioblastomas, p-p70S6K, but not with p-mTOR, clustered together with p-AKT implying that the downstream effect of p-AKT is primarily conveyed by S6K signaling through TSC2." (PMID 22530122, 2012). "In glioblastoma, this protective mechanism may at least partially be abrogated by overactive phosphoinositide-3-kinase (PI3K)-AKT signaling, which is an important upstream positive regulator of mTOR." (PMID 22825389, 2012). "Furthermore, the growth of renal cell carcinoma, glioblastoma multiforme, as well as non-small-cell lung cancer, pancreatic, colon, and breast cancers were synergistically reduced when EGFR inhibitors were combined with the mTOR inhibitor rapamycin." (PMID 18797454, 2008). "Non-Wnt pathways (e.g., PI3K/AKT/mTOR) contribute to its pro-survival roles in gastric, colorectal, and glioblastoma (GBM), where it enhances temozolomide resistance." (PMID 40821817, 2025). "In addition, biperiden produced, mainly, autophagy in glioblastoma cells, which could be explained by blocking MALT1 protease activity, which increases autophagy and culminates in lysosome-mediated cell death and concomitantly with the inactivation of mTOR." (PMID 36447028, 2022). "Molecular analysis of glioblastoma cell lines, patient-derived cell cultures and clinical samples from phase I clinical trials suggest that the expression of promyelocytic leukemia (PML) gene may be responsible for resistance to cytotoxicity of mTOR inhibition." (PMID 30374421, 2018). "To verify whether this peculiar crosstalk between mTOR and IDO1 observed in DAOY cells could be extended also to other high-grade or low-grade brain tumors, we evaluated the expression of the two molecules by WB on 4 glioblastoma and 2 ganglioglioma tissue specimens." (PMID 27174915, 2016). "Radiotherapy in combination with mTOR inhibition (temsirolimus) is an alternative schedule that has proved efficient in preclinical studies and is currently under evaluation in a clinical study of newly diagnosed glioblastomas in comparison to chemoirradiation and lack of MGMT methylation." (PMID 22530122, 2012).
glioblastoma (continued). "Carnosine blocks glioblastoma cell growth; this blockade is independent of the PI3K/Akt/mTOR (mammalian target of rapamycin) signaling pathway." (PMID 39063232, 2024). "Currently, there are various drugs available that target specific glioblastoma pathways (growth, invasion, migration) including but not limited to tyrosine kinase inhibitors (EGFR, mTOR, VEGF), NF-κB modulators, immunotherapeutics and nitrosoureas." (PMID 33316976, 2020). "The pathway mTOR, a key mediator of phosphatidyl-inositol-3-kinase (PI3K) signaling, has emerged as a compelling molecular target in glioblastoma patients, although clinical efforts to target mTOR have not been successful." (PMID 32770935, 2020). "Mammalian Target Of Rapamycin (mTOR), a key mediator of phosphatidyl-inositol-3-kinase (PI3K) signaling, has emerged as a compelling molecular target in glioblastoma patients, although clinical efforts to target mTOR have not been successful." (PMID 32770935, 2020). "In both glioblastoma cell lines, the analysis demonstrated no significant changes in the level of PI3K, Beclin1, and mTOR compared to control siRNA cells." (PMID 29439667, 2018). "However, in glioblastoma cells not expressing MGMT, resistance to TMZ was shown to be associated with a PI3K–mediated HOX/stem cell gene signature, and this resistance was reversed by inhibition of the PI3K signalling pathway using the dual pan-class I PI3K/mTOR inhibitor PI-103." (PMID 28704425, 2017). "Since neuroblastoma and glioblastoma are, with respect to PI3K/Akt/mTOR signaling, two very different entities, there is no a priori reason to assume that other tumors will not be subject to the principles discussed here." (PMID 26056598, 2014). "Preclinical studies suggested synergistic effects upon combined EGFR and mTOR pathway inhibition in non-SCLC and breast, squamous cell carcinoma, glioblastoma, colon, pancreatic cancer and biliary tract cancer." (PMID 20683448, 2010). "As the extensive crossover of the MAPK and PI3K/AKT/mTOR signalling cascades have been described thus far, it is no wonder that targeting broad effector molecules such as AKT, mTOR, or BRAF/MEK have proven difficult as a treatment strategy in glioblastoma." (PMID 37857607, 2023). "Moreover, the combination of sirolimus, an inhibitor of mTOR, and EGFR-TKIs did not improve the responsiveness in patients with recurrent glioblastomas." (PMID 31284441, 2019). "However, the effect of combining these drugs for treating glioblastoma, especially with respect to its effect on activating the PI3K/Akt/mTOR pathways has not been studied." (PMID 31841506, 2019). "Furthermore, as in our study on sarcoma, sensitization to DOX-induced apoptosis in glioblastoma was mainly due to inhibition of PI3K, but not of mTOR." (PMID 23300809, 2012).